NMS (neuromedin S)
Description:
Implicated in the regulation of circadian rhythms through autocrine and/or paracrine actions.
Tractability: Antibody: its Gene Ontology location is reachable by antibodies, with high confidence; UniProt places it where antibodies can reach, with medium confidence; UniProt predicts a signal peptide or a membrane-spanning region.
Gene: Protein-coding gene on chromosome 2 (100,470,482 to 100,483,280, forward strand). Ensembl gene ENSG00000204640.
Subcellular location: Secreted
Pathways (Reactome):
Signal Transduction: G alpha (i) signalling events; G alpha (q) signalling events; Peptide ligand-binding receptors
Gene Ontology:
Cellular component: extracellular region
Genetic constraint (gnomAD): Loss-of-function variants: 25 observed, 24 expected, observed/expected ratio (o/e) 1.04, 90% interval 0.76 to 1.45. The synonymous counts are far from expectation, so gnomAD's model fits this gene poorly and the ratio says little. Missense variants: 142 observed, 145.22 expected, observed/expected ratio (o/e) 0.98, 90% interval 0.85 to 1.12. Synonymous variants: 63 observed, 46.66 expected, observed/expected ratio (o/e) 1.35, 90% interval 1.1 to 1.66.
Homologues: Orthologues: chimpanzee NMS (100% identical), dog NMS (78% identical), macaque NMS (78% identical), guinea pig NMS (69% identical), rabbit NMS (67% identical), mouse Nms (63% identical), rat NMS (58% identical).
Diseases named in the same sentence as NMS in open-access papers:
NMS is named in the same sentence as 1 disease in open-access papers, as found by Europe PMC text mining. Sharing a sentence is not in itself a finding about the gene and the disease.
NMS shares sentences with these, for which no sentence is quoted: cancer (1 paper).